TXNIP (thioredoxin interacting protein)
Diseases named in the same sentence as TXNIP in open-access papers (continued):
Sharing a sentence is not in itself a finding about the gene and the disease.
lung fibrosis (2 papers, 2023 to 2024). "The results of this study revealed that the decrease of TXNIP in lungs apparently contributes to the pathogenesis of pulmonary fibrosis and that USP13 can target TXNP for deubiquitination and regulate its stability." (PMID 38529321, 2024). "To understand the role of TXNIP in pulmonary fibrosis, we focused on investigating TXNIP’s stability in lung fibroblasts." (PMID 38529321, 2024). "We showed that TXNIP levels were reduced in bleomycin-induced lung fibrosis and in TGF-β1-treated lung fibroblasts and epithelial cells." (PMID 38529321, 2024). "As TGF-β1 is important in development of lung fibrosis, we examined TXNIP levels under TGF-β1 treatment." (PMID 38529321, 2024). "To investigate if the reduction of TXNIP contributes to the pathogenesis of lung fibrosis, we first measured ROS levels in TXNIP-overexpressed lung fibroblasts." (PMID 38529321, 2024). "Our current results demonstrate the opposite phenomenon, indicating that TXNIP levels decreased in a bleomycin-induced lung fibrosis model and in response to TGF-β1." (PMID 38529321, 2024). "To investigate the role of TXNIP in the pathogenesis of lung fibrosis, we examined the TXNIP levels in lung tissues from PBS and bleomycin-challenged mice." (PMID 38529321, 2024). "With regard to scar formation, TXNIP was shown to be elevated in a murine model of pulmonary fibrosis, and the inhibition of TXNIP in this model led to the reduction in ROS and myoFB differentiation." (PMID 37111549, 2023). "Thus, this study reveals a molecular basis for development of small molecules that can regulate TXNIP stability to treat diseases such as cancers and lung fibrosis." (PMID 38529321, 2024). "As we demonstrated that reduction of TXNIP may contribute to pathogenesis of lung fibrosis, we further investigated the molecular regulation of TXNIP degradation." (PMID 38529321, 2024). "Thus, the reduction of TXNIP in lungs may promote fibrotic responses and contribute to the development of lung fibrosis." (PMID 38529321, 2024). "This study underpins the anti-fibrotic property of TXNIP in pulmonary fibrosis through attenuation of TGF-β1 signaling and emphasizes that TXNIP is unstable under TGF-β1 treatment, but can be stabilized by USP13." (PMID 38529321, 2024). "The role of TXNIP in lung fibrosis and molecular regulation of its stability have not been well studied." (PMID 38529321, 2024). "Re-analysis of GDS4902 and GDS5078 microarray databases indicates no signfinicant changes in TXNIP mRNA levels in bleomcyin-induced lung fibrosis model." (PMID 38529321, 2024). "The role of TXNIP in pulmonary fibrosis has not been well studied." (PMID 38529321, 2024). "Overexpression of TXNIP attenuated transforming growth factor-β1 (TGF-β1)-induced phosphorylation of Smad2/3 and fibronectin expression in lung fibroblasts, suggesting that decrease in TXNIP may contribute to the pathogenesis of lung fibrosis." (PMID 38529321, 2024).
malignant renal cell carcinomas (2 papers, 2020 to 2025). "In kidney cancer, benign oncocytomas are TXNIP-positive in most cases (90.2%), while TXNIP expression got lost in malignant renal cell carcinomas (ranging from 29.8 to 42.1%)." (PMID 33081035, 2020).
mesothelioma (2 papers, 2014 to 2025). A usually malignant and aggressive neoplasm of the mesothelium which is often associated with exposure to asbestos. "In mesothelioma cell lines with a stable knockdown of extracellular signal regulated kinase 2 (shERK 2), the expression of TXNIP was found to be down-regulated 4-fold." (PMID 24885895, 2014).
metastatic disease (2 papers, 2021 to 2024). "Importantly, some of these genes (THBS1, MAPKAPK2, CD9, TXNIP) were strongly associated with IL-6 signaling, indicating that IL-6 or its associated genes are coupled with metastatic tumors, in alignment with our previous findings." (PMID 34140316, 2021).
metastatic melanoma (2 papers, 2021 to 2022). A melanoma that has spread from its primary site to another anatomic site. "We first identified TXNIP as a PPARγ-regulated gene in a RNA-seq transcriptomic analysis of A375 human metastatic melanoma cell line described in7 (Primary data accession number: GSE115221)." (PMID 33846376, 2021).
multiple myeloma (2 papers, 2011 to 2026). "Therefore, TXNIP expression is higher in patients classified as having high-risk cytogenetic features according to the criteria established by the International Myeloma Working Group 2025 guidelines." (PMID 41545347, 2026). "We therefore propose that TXNIP may represent a novel and clinically relevant factor in myeloma." (PMID 41545347, 2026).
nephrosclerosis (2 papers, 2016 to 2025). Hardening of the kidney due to infiltration by fibrous connective tissue (fibrosis), usually caused by renovascular diseases or chronic hypertension. "Furthermore, public human GEO databases (GDS3712 and GDS3980) showed that TXNIP was increased in humans with nephrosclerosis and DM." (PMID 40610750, 2025). "The TXNIP transcript level was significantly upregulated in humans with nephrosclerosis and DM." (PMID 40610750, 2025).
ovarian failure (2 papers, 2021 to 2022). "Therefore, we hold the opinion that Mox inhibits TXNIP/NLRP3/caspase-1 signaling-medicated pyroptosis and alleviates ovarian failure in POF." (PMID 33613687, 2021).
papillary carcinoma (2 papers, 2014 to 2020). A malignant epithelial neoplasm characterized by a papillary growth pattern. "Immunohistochemistry to detect TXNIP protein expression was performed on paraffin-embedded tumor blocks of 13 well-differentiated primary papillary thyroid cancer (PTC) tumors and 8 ATC patient specimens." (PMID 24645981, 2014).
promyelocytic leukemia (2 papers, 2020). "TXNIP was initially described as 1,25-dihydroxyvitamin D3-upregulated protein 1 (VDUP1) in human promyelocytic leukemia HL-60 cells." (PMID 33081035, 2020).
retinal degeneration (2 papers, 2017 to 2020). Degeneration of the retina. "Loss of TXNIP provided significant protection in mice fed a HFD, showing significant protection from retinal degeneration and microvascular dysfunction due to reduced activation by the retinal endothelial cells of TXNIP/NLRP3 inflammasome." (PMID 33302545, 2020).
retinal ischemia (2 papers, 2019 to 2023). A ischemic disease that involves the retina. "In conclusion, it was suggested that Homer1 may protect against MCAO-induced retinal ischemia and RGCs pyroptosis by inhibiting endoplasmic reticulum stress-associated TXNIP/NLRP3 inflammasome activation after MCAO-induced retinal ischemia." (PMID 38069134, 2023). "In our study, Bip and CHOP proteins as markers of ER stress changed accordingly with the regulation of Homer1 in this experiment, verifying the role of ER stress in the TXNIP/NLRP3-mediated pyroptosis-signaling pathway after MCAO-induced retinal ischemia." (PMID 38069134, 2023). "Although it was found in this study that Homer1 can regulate ER stress-related TXNIP/NLRP3-mediated pyroptosis through the AMPK signaling pathway in the MCAO–retinal ischemia model, some limitations cannot be ignored." (PMID 38069134, 2023). "In this study, it was demonstrated that TXNIP/NLRP3-mediated pyroptosis also played an important role after retinal ischemia." (PMID 38069134, 2023). "Male C57Bl/J (WT) or TXNIP knockout (TKO) mice were subjected to retinal ischemia by increasing intraocular pressure for 50 min." (PMID 31443163, 2019). "In the present study, it was shown that TXNIP/NLRP3-mediated pyroptosis increased gradually and peaked 24 h after MCAO-induced retinal ischemia." (PMID 38069134, 2023). "It was shown that TXNIP/NLRP3-mediated pyroptosis was located predominantly in RGCs, which gradually increased after retinal ischemia and peaked at 24 h after retinal ischemia." (PMID 38069134, 2023).
sarcoma (2 papers, 2022 to 2024). A usually aggressive malignant neoplasm of the soft tissue or bone. "Notably, SD3 was enriched in the negative regulation of RIG‐I signalling with high expression of BTNL9 and TXNIP, indicating endogenous anti‐immune activation and an anti‐antigen presentation module in sarcoma." (PMID 39658531, 2024).
schizophrenia (2 papers, 2019 to 2022). A major psychotic disorder characterized by abnormalities in the perception or expression of reality. "The schizophrenia-like mouse model provided preliminary knowledge about the association between TXNIP expression and schizophrenia." (PMID 36291328, 2022). "We hypothesized that a persistent injection of MK801 (such as 7 days or more) instead of two injections might generate schizophrenia-associated lasting upregulation of TXNIP; however, this should be investigated in the future." (PMID 36291328, 2022). "The interaction of tumor suppressor genes TXNIP and AF1q may also contribute to risk for schizophrenia." (PMID 31660909, 2019). "We found that approximately 75% of FEDN schizophrenia patients displayed a relatively high plasma level of TXNIP." (PMID 36291328, 2022). "Although lacking postmortem tissues, our preliminary study examined the relationship between the plasma level of TXNIP and schizophrenia." (PMID 36291328, 2022). "TXNIP was significantly increased in the PFC of schizophrenia-like mice after MK801 administration, followed by oxidative stress." (PMID 36291328, 2022). "Combined with conditional knockout mice and schizophrenia samples, we aimed to investigate the function of TXNIP in healthy brain and psychiatric disorders, which are under-studied." (PMID 36291328, 2022). "First episode and drug naïve schizophrenia patients with a higher level of plasma TXNIP displayed severer psychiatric symptoms than patients with a low level." (PMID 36291328, 2022). "We also investigated the relationship between TXNIP and schizophrenia." (PMID 36291328, 2022). "Next, we investigated the expression of TXNIP in a schizophrenia-like mouse model." (PMID 36291328, 2022). "In the future, we need to follow up on the expression of TXNIP in patients during the prodromal phase, which could help us better understand its application as a biomarker of schizophrenia." (PMID 36291328, 2022). "Blocking the expression of TXNIP is needed to investigate whether schizophrenia-like behaviors could be recovered." (PMID 36291328, 2022). "Finally, we detected the relationship between TXNIP and schizophrenia based on a previously established schizophrenia-like mice model and clinical samples, consisting of the first episode and during naïve (FEDN) patients and healthy controls." (PMID 36291328, 2022). "Furthermore, we studied the relationship between TXNIP and schizophrenia using a schizophrenia-like mice model and clinical samples." (PMID 36291328, 2022). "The limitation of this part is that we could not demonstrate the causal effect between TXNIP and schizophrenia." (PMID 36291328, 2022). "There are no studies about the relationship between TXNIP and schizophrenia." (PMID 36291328, 2022).
synucleinopathies (2 papers, 2021 to 2024). "Collectively, these results indicate that MitoApo ameliorates the αSynagg-induced ERS and TXNIP/NLRP3 signaling axis in a cell culture model of α-synucleinopathy." (PMID 34276337, 2021). "Therefore, our studies unravel a previously unknown mechanism linking PKCδ, ERS, and the TXNIP/NLRP3 signaling axis to the microglial activation response in the context of α-synucleinopathy." (PMID 34276337, 2021). "It has been revealed that ROS induces an interaction between the leucine-rich repeats (LRRs) of NLRP3 and thioredoxin-interacting protein (TXNIP), which is necessary for autophagy regulation and affects PD-related synucleinopathy by hindering ATP13A2." (PMID 38338925, 2024). "To date, there is no published literature detailing TXNIP nor eIF2α-expression within microglia in the context of synucleinopathy." (PMID 34276337, 2021). "Together, our results suggest that inhibition of ERS and its downstream signaling mediators TXNIP and NLRP3 might represent novel therapeutic avenues for ameliorating microglia-mediated neuroinflammation in PD and other synucleinopathies." (PMID 34276337, 2021).
uveal melanoma (2 papers, 2020 to 2022). A melanoma derived from melanocytes of the uveal tract. "Meanwhile, lowly expressed TXNIP was linked to poor prognosis of DFS for the TCGA cases of CHOL (P = 0.010), KIRC (P = 0.002), SARC (P = 0.019), and uveal melanoma (UVM, P = 0.026)." (PMID 35843949, 2022).
abdominal aortic aneurysm (1 paper, 2026). Enlargement and ballooning of the vessel that supplies arterial blood to the abdomen, pelvis and legs. "Here, we define how stress-responsive mRNA methylation controls TXNIP expression and drives abdominal aortic aneurysm (AAA)." (PMID 41623483, 2026).
adrenocortical carcinoma (1 paper, 2016). "The downregulated genes comprised the thioredoxin-interactin protein (TXNIP), whose downregulation was also observed in HUVEC and H295R adrenocortical carcinoma cells after exposure to polybrominated diphenyl ethers." (PMID 26705709, 2016).
alcoholic liver diseases (1 paper, 2019). A disorder caused by damage to the liver parenchyma due to alcohol consumption. "TXNIP (thioredoxin-interacting protein) is a direct target of miR-148a and is overexpressed during alcoholic liver disease, activating NLRP3 inflammasome in hepatocytes, and caspase 1-mediated pyroptosis." (PMID 31507607, 2019).
ampullary carcinoma (1 paper, 2024). "In distal bile duct and ampullary carcinomas, high nuclear TrxR expression was associated with vascular (p = 0.001) and perineural (p = 0.021) invasion, and low cytoplasmic TxNIP expression was associated with perineural invasion (p = 0.025)." (PMID 39452470, 2024). "In the distal bile duct/ampullary carcinoma cohort, we observed a strong association between high cytoplasmic TxNIP expression and better overall survival, which remained significant in the multivariate Cox regression analysis." (PMID 39452470, 2024). "In the distal bile duct/ampullary carcinoma cohort, high cytoplasmic TxNIP and nuclear TrxR expression levels were significantly associated with age > 60 years (χ2 = 3.892, df = 1, p = 0.049 and χ2 = 5.091, df = 1, p = 0.024, respectively)." (PMID 39452470, 2024). "In the distal bile duct/ampullary carcinoma cohort, the median H-scores were 150 (range, 0–300), 166.7 (range, 0–300), 166.7 (range, 0–300), 66.7 (range, 0–250), and 66.7 (range, 0–250) for cytoplasmic Trx, nuclear Trx, cytoplasmic TxNIP, cytoplasmic TrxR, and nuclear TrxR, respectively." (PMID 39452470, 2024).
anaplastic carcinomas (1 paper, 2020). "In contrast, TXNIP was only weakly expressed in 12.5% of undifferentiated anaplastic carcinomas having a median survival of only months." (PMID 33081035, 2020).
atopic dermatitis (1 paper, 2025). "In atopic dermatitis models, quercetin shows potential as a targeted therapy, while coptisine alleviates inflammation by suppressing the TXNIP/NLRP3 inflammasome." (PMID 40612058, 2025).
autism spectrum disorder (1 paper, 2025). A spectrum of developmental disorders that includes autism, and Asperger syndrome. "This boy suffered from recurrent hypoglycaemia, neonatal muscular hypotonia and failure to thrive, and was under investigation for autism spectrum disorder, similar to our patient with the c.642_643insT TXNIP (p.Ile215Tyrfs*59) variant." (PMID 41116060, 2025).
B cell lymphoma (1 paper, 2020). "Indeed, due to inhibitory effects on cell growth, TXNIP is classified as a tumor suppressor, and downregulation of TXNIP expression in a variety of human cancers, including B cell lymphoma, has been reported." (PMID 32017809, 2020).
bacteremia (1 paper, 2015). "Also, in P. aeruginosa-induced bacteremic shock, TXNIP exacerbates septic shock associated with bacteremia in a mouse model." (PMID 26178806, 2015). "This is discussed further, below, along with the contribution of TXNIP to host response to P. aeruginosa bacteremia by recruitment of neutrophils in mice." (PMID 26178806, 2015).
bone metabolic disorders (1 paper, 2022). "Thus, further preclinical and clinical investigations are essential for understanding TXNIP-specific inhibitors and developing new promising treatments to mitigate the health problems associated with bone metabolic disorders." (PMID 36059548, 2022). "Considering the necessity and multiple roles of TXNIP in bone cells, targeting molecules or signaling pathways that interact with TXNIP is a potential strategy for treating and preventing bone metabolic disorders." (PMID 36059548, 2022).
brain tumours (1 paper, 2020). "TrxR, Trx and TxNIP expression displayed a mixture of diffuse and granular cytoplasmic staining in all types of brain tumours." (PMID 32418115, 2020).
Burkitt lymphoma (1 paper, 2025). A rare form of malignant mature B-cell non-Hodgkin lymphoma. "In Burkitt lymphoma (BL), KLF4 acts as a tumor suppressor by reducing MYC expression and its downstream target EZH2 while activating tumor suppressors such as TXNIP." (PMID 39995670, 2025).
cancers of the respiratory system (1 paper, 2020). "TXNIP expression in cancers of the respiratory system and others." (PMID 33194655, 2020).
chronic gastritis (1 paper, 2025). Inflammation of the stomach that is chronic in nature. "CAG mice infected with Helicobacter were given Chaenomeles speciosa total triterpenoids, and their chronic gastritis and atrophy glands were improved by the reduction of thioredoxin-interacting protein (TXNIP), NLRP3, pro-caspase-1, and caspase-1 levels." (PMID 40264171, 2025).
Cirrhosis (1 paper, 2023). A chronic disorder of the liver in which liver tissue becomes scarred and is partially replaced by regenerative nodules and fibrotic tissue resulting in loss of liver function. "Further study is required to understand the underlying molecular mechanisms through which TXNIP is regulated by CHIP and how CHIP tightly controls the suppressive response to cirrhosis." (PMID 36830016, 2023).
colorectal adenocarcinoma (1 paper, 2024). The most common type of colorectal carcinoma. "The MondoA dependent relationship between TXNIP and GDF15 in response to oxaliplatin-induced ROS can be used to predict aggression and treatment sensitivity in colorectal adenocarcinoma." (PMID 39103698, 2024). "Here, in colorectal adenocarcinoma (CRC) we identify oxaliplatin-induced Thioredoxin-Interacting Protein (TXNIP), a MondoA-dependent tumor suppressor gene, as a negative regulator of Growth/Differentiation Factor 15 (GDF15)." (PMID 39103698, 2024).
deep venous thrombosis (1 paper, 2025). "Furthermore, in deep venous thrombosis rats, TRX expression was suppressed while TXNIP and NLRP3 were elevated, wherein siTXNIP or MCC950 injection rescued the injury of a vein induced by deep venous thrombosis by improving the physiological changes and reducing the inflammatory reaction." (PMID 40643515, 2025).
dengue virus infection (1 paper, 2025). "Consistent findings were also observed in DENV2-infected cells, where dengue virus infection promoted TXNIP protein expression as early as 6 h post-infection in primary mouse blood monocytes cells." (PMID 40628121, 2025). "We found that dengue virus infection also promotes TXNIP overexpression, and TXNIP overexpression significantly enhances dengue virus infection." (PMID 40628121, 2025). "Conversely, TXNIP knockout via CRISPR-Cas9 or knockdown via shRNA inhibits dengue virus infection." (PMID 40628121, 2025).
diabetic encephalopathy (1 paper, 2018). A brain disease that is characterized by functional impairment of cognition, cerebral signal conduction, neurotransmission and synaptic plasticity, and underlying structural pathology associated with diabetes. "We also found inflammation and ER stress were associated with diabetic encephalopathy, as ER stress, TXNIP, and NLRP3 inflammasome is activated in the hippocampus, but Gas treatment could reverse these changes." (PMID 30544722, 2018).